AXL (AXL receptor tyrosine kinase)
Diseases named in the same sentence as AXL in open-access papers (continued):
Sharing a sentence is not in itself a finding about the gene and the disease.
tumor (continued). "Inhibition of AXL using both shRNA and a soluble AXL, AVB-500, showed significant decreases in tumor growth and metastasis." (PMID 36980768, 2023). "To further examine the possible clinical translation of AXL inhibition in the clinic, we tested the efficacy of AVB-500, a soluble AXL receptor, in reducing AXL activation and tumor growth." (PMID 36980768, 2023). "In the lung, however, metastatic cells are reactivated by aged fibroblasts through secreted sFRP1, which is an antagonist of Wnt5a, resulting in decreased AXL signaling, enhanced MER activation and tumor cell proliferation." (PMID 37296983, 2023). "The right panel shows a combination therapy of ROS1 and AXL inhibitors blocks AKT signaling, thus leading to tumor cell death." (PMID 37727007, 2023). "The secreted protein genes WNT5A, VEGFA, and SEMA3A, and the receptor genes AXL, TNFRSF10B and IGF1R were mainly expressed by tumor cells." (PMID 37823774, 2023). "Signaling pathways downstream Gas6/AXL signaling, including PI3K/AKT/mTOR, NF-κB, JAK/STAT3 and RAS/RAF/MEK/ERK, play critical roles in tumor cell cycle regulation, malignancy and drug resistance." (PMID 37265798, 2023). "The multitargeted TKI cabozantinib has shown antitumor activity against tumor cells expressing activated (phosphorylated) receptors MET and AXL (P-MET and P-AXL), including sunitinib-resistant human RCC cells." (PMID 36982721, 2023). "Jeon and co-workers demonstrated the AXL suppressor Q702 decreased the expression of TAM signature genes and upregulated MHC-I signature genes in tumor samples, and also reported upregulated CD8 T cell and NK cell signature genes in a time-dependent manner." (PMID 37265798, 2023). "GAS6 and the cognate receptor AXL, a TAM (TYRO3, AXL, MER) RTK family member, play a major role in EMT, therapy resistance, and metastasis in different tumour types." (PMID 37259089, 2023). "A recent study demonstrated that combining MWA with CAR-T cells targeting a receptor tyrosine kinase (AXL) (AXL-CAR T cells) in NSCLC patient-derived xenografts, enhances the infiltration, activation, persistence, and tumor killing." (PMID 36717905, 2023). "Inhibitors that target MET, AXL, VEGFR-2, FLT3 and MERTK are becoming research and development hotspots owing to their effect on promoting tumor development and progression." (PMID 36341335, 2022). "AXL protein expression was significantly higher in PTC than in normal thyroid tissue, and positive staining was primarily observed in tumour cell membranes and cytoplasm." (PMID 36203174, 2022). "Since KRAS mutations can lead to impaired mitochondrial respiration, this sophisticated reciprocal signaling node restores mitochondrial respiration in KRAS mutant tumor cells via SHH, IGF1R/AXL, and AKT." (PMID 36612058, 2022). "In tumor-bearing mice, the expressions of TYRO3, AXL, and MERTK, and their ligands increased >20 folds in M-MDSCs and >15 folds in PMN-MDSCs." (PMID 36131911, 2022). "To further explain the enhanced antitumour ability of AXL-CAR T cells in vivo, we sacrificed 5 mice in the combination and AXL-CAR T groups on day 33 and 42 and sorted tumour-infiltrating CAR T cells to perform a series of tests." (PMID 36261437, 2022). "Taken together, these results indicate that AXL inhibition by SKI-G-801 with SoC treatment has significant benefits with respect to the inhibition of tumor growth and improved survival, in C3PQ tumor model." (PMID 35356198, 2022). "On the other hand, a previous study has demonstrated that Se/FO can enhance the anticancer activity of bevacizumab by inhibiting tumor EGFR, TβR, and AXL proteins in breast tumor-bearing mice." (PMID 36547898, 2022). "Kinase profiling using KINOMEScan has revealed that, in addition to targeting FLT3/AURK signaling pathways, MET and AXL, two kinases that play a critical role in HCC tumor progression, invasion, and metastasis, were potently inhibited by DBPR114." (PMID 35062934, 2022).
tumor (continued). "The combination regimen of trametinib and AXL/MET/VEGFR inhibitor glesatinib showed initial efficacy both in vitro and in vivo (92% reduction in tumor volume)." (PMID 35343367, 2022). "Thus, TC1 and C3PQ cell lines were treated with SKI-G-801, an AXL inhibitor, to investigate the efficacy of a chemo- and immunotherapy in order to prove potential effects of AXL inhibitor on therapeutic strategy and anti-tumor activity on LUSC and LUAD through a model-based analysis." (PMID 35356198, 2022). "AXL-CAR T cells alone only moderately suppressed tumour growth, but their combination with MWA enabled effective AXL-CAR T cell therapy that reduced HA, increased vascularisation, decreased IFP, and alleviated hypoxia." (PMID 36261437, 2022). "These favourable changes that enriched AXL-CAR T cells and enhanced their functional properties have been previously reported in preclinical tumour models." (PMID 36261437, 2022). "By using AXL+ tumor initiating cells that display partial EMT, it was suggested that AXL prepared the metastatic niche by activating lung fibroblasts via the secretion of THSB2." (PMID 35158733, 2022). "Both AXL and MERTK play key roles in tumor cell proliferation, migration, invasion, survival and treatment resistance." (PMID 35062934, 2022). "Sitravatinib (MGCD516), a spectrum-selective receptor tyrosine kinase inhibitor targeting TAM (TYRO3, AXL, MERTK) and split kinase family receptors, has demonstrated preclinical anti-tumor activity and modulation of tumor microenvironment." (PMID 35767205, 2022). "The qRT-PCR results revealed that AXL (p = 0.0308), FAS (p = 0.0134), TNFRSF1B (p = 0.0250), and CDKN2A (p = 0.0224) mRNA expression were considerably greater in tumor tissues." (PMID 36186479, 2022). "Responses were observed in patients with RCC and NSCLC, and included patients with tumor RET rearrangements, and MET, CBL and AXL alterations." (PMID 35767205, 2022). "CT053 (free-base form of CT053PTSA) inhibited MET, AXL, VEGFR2, FLT3 and MERTK phosphorylation and suppressed tumor cell angiogenesis by blocking VEGF and HGF, respectively, in vitro." (PMID 36341335, 2022). "Tumor-bearing mice in the TB-G-N group showed markedly lower levels of p-EGFR, TGF-β, p-AXL, Wnt3a, and β-catenin proteins compared to those in the TB-G group." (PMID 36547898, 2022). "Expression of AXL and CDCP1 in tumor samples was examined by immunohistochemical (IHC) analysis after tumors were surgically resected in 6 patients (#1, #2 with wild-type EGFR; #3, #4 with EGFRdel19; #5, #6 with L858R EGFR) before chemotherapy." (PMID 35643725, 2022). "Together, compared with monotherapy, MWA combined with AXL-CAR T cells exhibited superior local and systemic CDX (cell-derived xenografts) tumour regression under a good safety threshold in NSG mice." (PMID 36261437, 2022). "In contrast, compared with the outcomes of monotherapies, MWA combined with AXL-CAR T cells efficiently suppressed tumour growth and led to better tumour regression at the endpoint." (PMID 36261437, 2022). "In pericytes, paracrine activation of AXL by GAS6 was shown to regulate the expression of the pro-angiogenic protein Cyr61, leading to angiogenesis and tumor growth." (PMID 35158733, 2022). "Pericyte-1 was enriched in the tumor fraction and characterized by higher expression of genes related to a pro-inflammatory capillary phenotype (RGS5, KCNJ8, AXL, ABCC9, PDGFRB, and THY1)." (PMID 36180422, 2022). "AXL has emerged as a therapeutic drug target for TNBC treatment, and AXL-CAR-T cell therapy led to significant in vitro cytotoxicity and cytokine secretion as well as a reduction in tumor growth in an TNBC xenograft mouse model." (PMID 35795050, 2022). "Upon binding to AXL, GAS6 activates downstream signaling pathways and promotes tumor cell survival, proliferation, migration, and other activities." (PMID 36313732, 2022).
tumor (continued). "The present study further demonstrates that the combination treatment modulates the expression of the tumor receptor signaling molecules, including TGF-β/TβR-2, AXL/Gas6, and Wnt/FZD/β-catenin/GSK-3β, in LLC1 tumor tissues." (PMID 36547898, 2022). "In the last decade, co-expression of AXL and GAS6 was discovered on vascular cells present in various tumor types." (PMID 34884986, 2021). "Since its discovery, AXL has been shown to be involved in a wide range of signaling pathways such as PI3/AKT, MAPK, and SNAIL/EMT, promoting tumor cell survival and proliferation, as well as tumor migration and invasiveness." (PMID 34877810, 2021). "Densitometry analysis showed that five cytokines, IL-4, AXL, IL-1β, IL-9, Exotaxine-2 and IL2, were upregulated, and two cytokines, PF4 and IL-6, were downregulated in the tumor environment of JEG3-Sh-NLRP7 cells." (PMID 34203890, 2021). "AXL is a critical player in cancer cell EMT and the development of tumor metastasis and drug resistance in HCC." (PMID 34948046, 2021). "We found that several pro-tumor markers are increased in cancer tissues, including CD163, CD206, SIRPα, LILRB1, SIGLEC10, AXL, MERTK, and MARCO." (PMID 34778091, 2021). "Our current model summarizes these data, which suggest that BMI1 promotes tumor cell growth by inhibiting LATS1/2 phosphorylation and allowing YAP/TAZ/TEAD to transcribe canonical target genes (such as AXL, CYR61, and CTGF)." (PMID 33523558, 2021). "R428, an inhibitor of AXL, significantly abolished the increased tumor volume, liver metastasis, and vessel metastasis in the xenograft nude mice inoculated subcutaneously with HCC-LM3 cells plus HUVEC-AXL-OE or HUVEC-AXL-NC cells." (PMID 34123800, 2021). "Growth arrest-specific protein 6 can be derived from BMSCs or osteoblasts and plays an important role in the progression of tumor cells dormancy and reactivation by being combined with TAM receptors such as AXL and Tyro3." (PMID 34712663, 2021). "Tumor-derived single-cell suspension was stained with antibodies against CD45, CD31, EpCAM, and AXL." (PMID 34254585, 2021). "Activation of AXL and/or MERTK leads to signaling cascades that are important for tumor progression." (PMID 34830794, 2021). "GL21.T, a selective RNA-based aptamer, bound to the ectodomain regions of AXL (Kd = 12 nM) and reduced catalytic activity and AXL-dependent signaling, inhibited cellular migration and invasion, and reduced NSCLC tumor volume by 68.2% in vivo." (PMID 34830794, 2021). "MET inhibitor cabozantinib (also inhibits VEGFR2, AXL, KIT, RET) has been studied as an inhibitor of angiogenesis and tumor growth in many tumor diseases." (PMID 34212564, 2021). "We also showed that higher expression of AXL was significantly associated with poor prognosis of patients with TNBC and that a humanized anti-AXL monoclonal antibody could inhibit oncogenic phenotypes in vitro and reduce tumor formation in xenograft mouse models." (PMID 34439388, 2021). "CAF-mediated EMT, which is strongly correlated with the expression of AXL, TWIST2 and ADAM12 from the IMS, can result in biomechanical and biochemical changes that facilitate tumor immune escape, invasion, and metastasis." (PMID 33542239, 2021). "Of the 16 kinases originally identified in the tumour dataset, 6 were also found to be differentially expressed in the cell line panel: AKT3, MYLK, PRKD1, AXL, NUAK1 and DCLK1." (PMID 33673003, 2021). "AXL dimerizes with and phosphorylates EGFR to promote activation of the PLCγ-PKC-mTOR signaling cascade and tumor cell survival." (PMID 34830794, 2021). "It was demonstrated that osteoblast-derived GAS6 induces AXL expression in tumor cells, which suggests that paracrine GAS6/AXL signaling promotes survival, inhibits apoptosis, and mediates homing of tumor cells to the bone." (PMID 34778071, 2021).
tumor (continued). "The inhibition of AXL abated EMT phenotypic features and suppressed tumor proliferation and migration, positing AXL as a possible therapeutic target to overcome docetaxel resistance." (PMID 33672595, 2021). "Activation of AXL signaling has profound effects on promoting cell proliferation, migration and invasion, epithelial-mesenchymal transition (EMT) and tumor angiogenesis." (PMID 34439388, 2021). "It is possible that in tumour microenvironment, where the level of GAS6 is high, AXL takes a central stage." (PMID 34638349, 2021). "AXL receptor tyrosine kinase is highly expressed in H1299-sdCSCs and AXL knockdown with siAXLs significantly reduced tumour sphere formation and ALDH1A1 and SNAI2 (Slug) expression." (PMID 32051483, 2020). "In the present study, treating MPNST with AXL knockdown in combination with a MEK1/2 inhibitor reduced cell viability, cell proliferation, and tumor growth." (PMID 33283192, 2020). "In contrast, combined treatment with subtherapeutic doses of doxorubicin and an AXL inhibitor, BGB324, decreased tumor growth in an AML xenograft model." (PMID 32346605, 2020). "Here we demonstrate that INCB081776, currently in phase 1 clinical trials, is a highly selective inhibitor of AXL and MERTK and functions to inhibit AXL and MERTK through immunomodulatory as well as tumor-directed signaling mechanisms." (PMID 33425754, 2020). "For example, AXL, a member of the TAM receptor tyrosine kinase family, is an inducer of tumor cell plasticity and its expression increases tumor cell invasion and metastasis by promoting T cell exclusion." (PMID 35582437, 2020). "Based on the clear roles of AXL and MERTK in both immunosuppression and tumor-promoting mechanisms, we set out to develop a potent and selective small molecule dual inhibitor of both AXL and MERTK." (PMID 33425754, 2020). "Conversely, MPNST PDX tumors treated with the small molecule AXL inhibitor, BMS777607, resulted in decreased tumor volume when compared to the control group." (PMID 33283192, 2020). "The p-AXL levels were well correlated with the ALDH1A1 and SLUG levels in the tumours, with r values of 0.87 and 0.65." (PMID 32051483, 2020). "In cancer, AXL has been shown to promote epithelial to mesenchymal transition (EMT), metastasis formation, drug resistance, and a role for AXL in modulation of the tumor microenvironment and immune response has been identified." (PMID 32148495, 2020). "ANKRD1 was abundant in the tumour centre, while AMOTL2 and AXL were higher at periphery, where C3-positive microglia were also observed." (PMID 32404936, 2020). "Oral administration of EGCG and green tea extract (GTE) inhibited tumour growth in mice and reduced p-AXL, ALDH1A1, and SLUG in tumours." (PMID 32051483, 2020). "Reciprocally, hMENA/hMENAΔv6 regulates AXL expression in tumor cells, thus sustaining GAS6‐AXL axis, reported as crucial in EMT, immune evasion, and drug resistance." (PMID 32909687, 2020). "Knockdown of AXL, one of the YAP-TEAD target genes, decreases the growth and invasiveness of tumor xenographs." (PMID 33121449, 2020). "Here, we report a novel function of hMENA/hMENAΔv6 isoforms in tumor‐promoting CAFs and in the modulation of pro‐tumoral cancer cell/CAF crosstalk via GAS6/AXL axis regulation." (PMID 32909687, 2020). "Cabozantinib plays important roles in tumor cell proliferation and tumor neovascularization targeting MET, vascular endothelial growth factor receptor (VEGFR), AXL, and RET." (PMID 33194654, 2020). "+DDR2/+COL1 tumours also showed higher levels of CYR61 and AXL (1.58 and 1.42 folds, respectively) than −DDR2/+COL1 tumours." (PMID 32047176, 2020). "Dual targeting of AXL and MERTK led to a more potent inactivation of downstream signaling and reduced tumor growth in vivo compared with targeting either kinase alone." (PMID 33425754, 2020).
tumor (continued). "It has also been reported that AXL and MET are involved in acquired resistance to sunitinib and that cabozantinib has anti-tumor activity against sunitinib-resistant cells both in vitro and in vivo." (PMID 32055714, 2020). "H1299 tumor-bearing SCID mice were dosed with INCB081776 at dose levels of 3, 10, or 30 mg/kg, and tumors were evaluated for pAXL and total AXL expression." (PMID 33425754, 2020). "In summary, these data demonstrate that AXL/MERTK inhibition with INCB081776 hinders tumor growth by two distinct mechanisms—reversal of immunosuppression and ablation of intrinsic tumor cell survival signaling." (PMID 33425754, 2020). "Most of the AXL signaling is triggered by its ligand, growth arrest-specific gene 6 (GAS6); however, hypoxic conditions in the tumor microenvironment also play a critical role in the activation of GAS6-AXL signaling." (PMID 33374832, 2020). "AXL, the high-affinity ligand growth arrest-specific protein 6 (GAS6), is involved in multiple tumor processes, including proliferation, angiogenesis, invasion, metastatization, immune regulation, stem cell maintenance, EMT, and drug resistance." (PMID 33072597, 2020). "Particularly, AXL and MET cooperation, found in different tumor contexts, is correlated to increased tumor progression and migration." (PMID 33182542, 2020). "In this review, we will discuss the function of TYRO3, AXL and MERTK on all cells in the tumor micro-environment, with a special focus on T cells." (PMID 31664482, 2020). "Recently, one study demonstrated both circulating tumor cells exhibiting an active EMT status (vimentin+ and EGFR+) and tumoral expression of AXL mRNA as prognostic factors for OS and RFS of patients with early stage resectable NSCLC." (PMID 32674274, 2020). "MET and AXL activate common downstream signaling pathways, including PI3K/AKT and MAPK/ ERK networks, leading to tumor growth, metastasis, drug resistance, immune suppression, and the stem cell phenotype." (PMID 34766112, 2020). "TYRO3, AXL, and MERTK constitute the TAM family of receptor tyrosine kinases, which play important roles in tumor growth, survival, cell adhesion, as well as innate immunity, phagocytosis, and immune-suppressive activity." (PMID 33425754, 2020). "Since p-AXL is an essential factor for stemness, we examined the inhibitory effect of EGCG on tumour growth in H1299 cells in vivo using a mouse xenograft model." (PMID 32051483, 2020). "GAS6, AXL, and Cofilin-1 are overexpressed, but because of tissue-specific functions of claudins family, Claudin-1 may have a different role in various cancers; depending on the origin of cancer cells and the adjacent tumor microenvironment, it may increase or decrease in various cancers." (PMID 31700829, 2019). "The expression levels of AXL, GAS6, Claudin-1, and Cofilin-1 genes were investigated in a fresh, frozen tumor sample and normal adjacent tissue by real-time PCR (RT-PCR)." (PMID 31700829, 2019). "In the DNET, considered as a benign grade I tumour, we found high expression levels of ErbB3, FGFR2, FOLH1 and AXL." (PMID 31747973, 2019). "AXL inhibition by NPS1034 resensitized the cells to osimertinib treatment and resulted in reduced tumor size and delayed tumor growth compared to osimertinib alone." (PMID 31694201, 2019). "It is unclear, however, whether AXL is an inducer or effector of the EMT process and whether AXL inhibition, combined with an EGFR-TKI, is able to overcome the acquired resistance to EGFR-TKIs induced by EMT, a feature that may be closely associated with tumor heterogeneity." (PMID 30651547, 2019). "Together, suggest that AXL and/or RAGE positively affect the binding of intravasating tumor cells with the ECM on the vessels within GemOE tumors." (PMID 31844158, 2019). "The levels of AXL and of GAS6 mRNA in tumor tissue were evaluated by immunohistochemistry and chromogenic in situ hybridization, respectively." (PMID 31419057, 2019).